PDK1 (pyruvate dehydrogenase kinase 1)
Diseases named in the same sentence as PDK1 in open-access papers (continued):
Sharing a sentence is not in itself a finding about the gene and the disease.
colorectal cancer (34 papers, 2012 to 2026). A primary or metastatic malignant neoplasm that affects the colon or rectum. "PDK1 is overexpressed in many cancers, in colorectal cancer its aberrant upregulation is associated with poor prognosis and increased liver metastasis." (PMID 41488637, 2025). "Extracellular vesicles produced by L. paracasei (LpEVs) have been demonstrated to reduce colorectal cancer cell proliferation and induce apoptosis through the PDK1/AKT/Bcl-2 pathway." (PMID 38326490, 2024). "In our previous study, we determined vitamin C was able to induce HIF1a hydroxylation and degradation, downregulating GLUT1 and PDK1 in KRAS mutant colorectal cancer." (PMID 38425123, 2024). "A previous study suggested that WNT signaling activates the transcription of PDK1 to promote aerobic glycolysis in colorectal cancer." (PMID 38733179, 2024). "WNT/β‐catenin signaling pathway activates PDK1 to promote aerobic glycolysis in colorectal cancer cells." (PMID 38733179, 2024). "It has been reported that Wnt signaling up-regulates pyruvate dehydrogenase kinase-1 (PDK1) in colorectal cancer cells, leading to the enhanced glycolysis through the inhibition of pyruvate dehydrogenase (PDH) activity." (PMID 38684876, 2024). "Further, they can inhibit the growth of colorectal cancer cells in vivo and in vitro by inducing apoptosis through the 3-phosphoinositide-dependent protein kinase-1 (PDK1)/AKT/Bcl-2 signaling pathway." (PMID 36613399, 2023). "According to reports, SPRY4-IT1 promotes the survival of colorectal cancer cells by regulating PDK1-mediated glycolysis." (PMID 34220962, 2021). "Here, we report that HsA is a PDK1 inhibitor can reduce the growth of colorectal cancer and consequent activation of mitochondrial ROS-dependent apoptotic pathway both in vivo and in vitro." (PMID 33318678, 2020). "Although more pharmacological studies and clinical evidence are required, HsA has shown a potential candidate as a novel PDK1 inhibitor for colorectal cancer treatment." (PMID 33318678, 2020). "As a key glycolysis enzyme, the significance of pyruvate dehydrogenase kinase 1 (PDK1) in the development of colorectal cancer (CRC) remains unknown." (PMID 31506552, 2019). "In conclusion, our data suggest that BRAFV600E driven colorectal cancers have fragmented mitochondria which confers glycolytic phenotype and growth advantage to these tumors, and such phenotype is dependent at least in part on PDK1- thus highlighting a potential therapeutic target." (PMID 33738242, 2020). "The non-SMC condensin II complex subunit D3 elevates E2F1 levels and enhances its recruitment to the promoter regions of PDK1 and PDK3, inhibiting pyruvate dehydrogenase activity and the tricarboxylic acid cycle in colorectal cancer." (PMID 41158756, 2026). "Accordingly, reduced PDK1 activity activates PDH, increasing TCA cycle flux and promoting colorectal cancer cell apoptosis." (PMID 41488637, 2025). "Upon mitochondrial entry, PGK1 acts as a protein kinase to phosphorylate PDK1, thereby inhibiting PDH, reducing TCA flux, and enhancing colorectal cancer cell proliferation." (PMID 41488637, 2025). "We also made similar observations on MAPK4 enhancing PDK1 protein levels in human non-small cell lung cancer H1299 and H157 cells, colorectal cancer HCT116 cells, and prostate cancer DU145 cells, suggesting the MAPK4-PDK1 axis beyond TNBC." (PMID 37531320, 2023). "Synthesized compounds were designed by docking based virtual screening (DBVS) of a previous constructed compound library against protein targets, known for their important role in colorectal cancer signaling: MEK1, ERK2, PDK1, VEGFR2." (PMID 30234098, 2018). "This counterintuitive result was well exemplified by the cases of ZEB2 and RAS in the EMT regulatory network, IRS in the signaling network of EGF-EGFR and insulin-IR, MEK and GRB2 in the signaling network of T-LGL leukemia survival, p21 and PDK1 in F2013, and MEK in C2016 colorectal cancer networks." (PMID 31582789, 2019).
colorectal cancer (continued). "Similarly, in breast and colorectal cancers, B7-H3 exerts comparable effects by inhibiting Nrf2, thereby regulating critical metabolic enzymes such as hypoxia-inducible factor 1-alpha (HIF1α), lactate dehydrogenase A (LDHA), and pyruvate dehydrogenase kinase 1 (PDK1)." (PMID 40214484, 2025). "The Kaplan–Meier survival analysis revealed that low expression of NDUFS1, PDP1(rather than PDK1), and PDH, was correlated with poor prognosis respectively in colorectal cancer patients who received radiotherapy." (PMID 34489398, 2021).
glioblastoma (34 papers, 2015 to 2025). The most malignant astrocytic tumor (WHO grade IV). "The AKT3-174aa peptide, encoded by circ-AKT3 expressed in glioblastoma, can bind to PDK1 and reduce threonine phosphorylation at AKT308, thus participating in the inhibition process of glioblastoma." (PMID 39199340, 2024). "LncRNAs proximal to the X-inactive specific transcript (JPX) decrease the m6A level and increase the stability of phosphoinositide-dependent kinase-1 (PDK1) mRNA by recruiting FTO to PDK1 mRNA, facilitating aerobic glycolysis in glioblastoma multiforme." (PMID 38560499, 2024). "For example, circAKT3 has a predicted ORF and encodes a small 174-amino acid peptide, AKT3-174aa, which competitively binds p-PDK1 to inhibit downstream targets of p-PDK1, suppressing glioblastoma tumorigenicity." (PMID 37828589, 2023). "They found that miR-128-3p inhibited lactate synthesis, elevated ROS, and impaired mitochondrial activity in glioblastoma cells by targeting Pyruvate Dehydrogenase Kinase 1 (PDK1)." (PMID 36793341, 2022). "To rescue the TGF-β1-induced reduction in mitochondrial oxidative phosphorylation, we treated glioblastoma cells with siRNA against PDK1, a mitochondrial respiration-related gene that was overexpressed under the action of TGF-β1." (PMID 34257808, 2021). "Simultaneously, to maintain ATP levels during hypoxic conditions, glioblastoma cells upregulate PDK1 to reduce flux through the Krebs’s cycle and electron transport chain (ETC), thus favoring glycolysis." (PMID 34831136, 2021). "PDK inhibitor dichloroacetate (DCA) has been reported to inhibit PDK1 signaling and exert strong anti-tumor effects in glioblastoma." (PMID 26593251, 2016). "Dichloroacetate (DCA) is a relatively weak inhibitor of PDK1 and has been shown to inhibit tumor growth in glioblastoma." (PMID 26593251, 2016). "Similarly, lncRNA JPX facilitated aerobic glycolysis through the FTO/PDK1 axis, thus conferring resistance to temozolomide in glioblastoma multiforme (GBM) cells." (PMID 35843942, 2022). "Besides, genetic inhibition of LDHA and PDK1 reversed the TGF-β1-induced glioblastoma cells' migration and invasion." (PMID 34257808, 2021). "In glioblastoma, glucose uptake and lactate output was even more expressive in CSCs than in the tumor bulk, in addition to upregulation of pyruvate dehydrogenase kinase-1 (PDK-1) expression levels." (PMID 34359950, 2021). "In addition, dichloroacetate, a pyruvate dehydrogenase kinase 1 inhibitor, together with radiotherapy can effectively sensitize glioblastoma cells by inducing the cell-cycle arrest at the G2/M phase." (PMID 32231148, 2020). "As a result, AToMI analysis revealed AKT and mitochondrial pyruvate dehydrogenase kinase PDK1 and PDK4 as kinase targets of staurosporine derivatives UCN-01, CEP-701, and K252a that synergized with PP2A activation across heterogeneous glioblastoma cells." (PMID 35963891, 2022). "Glioblastoma neurospheres exposed to a hypoxic environment show a 10-fold increased expression of PFKFB3, as well as upregulation of LDHA, pyruvate dehydrogenase kinase 1 (PDK1), and HK-2, via HIF-1α signaling, particularly within the necrotic core." (PMID 34831136, 2021). "Dichloroacetate, a pyruvate dehydrogenase kinase 1 inhibitor, reverses increased glycolysis activity and reduces TMZ resistance in glioblastoma." (PMID 34209254, 2021). "Our previous results have shown that HIF1α regulates the PDK1/ EGFR interaction in the mitochondria and transcriptionally regulates PDK1 in glioblastoma." (PMID 28410193, 2017). "Besides, lncRNA JPX stabilizes PDK1 mRNA by enhancing FTO-mediated demethylation of PDK1 mRNA, thereby promoting aerobic glycolysis and temozolomide resistance of glioblastoma multiforme cells." (PMID 38560499, 2024). "Immunofluorescence staining of glioblastoma cells transfected with Flag-tagged AKT3-174aa also supported the co-localization of AKT3-174aa with p-PDK1, suggesting that AKT3-174aa preferred to inhibit thr308 of AKT by interacting with p-PDK1." (PMID 36091137, 2022).
glioblastoma (continued). "Similarly, glioblastoma cells treated with GSK2837808A (GSK, 10 μM), a selective inhibitor of LDHA and Dichloroacetate (DCA, 20 μM), a selective inhibitor of PDK1, reversed the EMT protein markers induced by TGF-β1." (PMID 34257808, 2021). "Our bioinformatics studies by Targetscan 7.1 and miRwalk 2.0 site have predicted that miR-548x and miR-4698 could simultaneously target 3ʹUTR of PI3KCB, PI3KCA, PDK1, AKT1, mTOR, MDM2, Rheb, and CREB1 genes that some of them were upregulated in glioblastoma sample according TCGA deta." (PMID 32005873, 2020). "According to our bioinformatics studies in the TargetScan 7.1 and miRwalk 2.0 database, we predicted that some miRNAs, as well as miR-548x and miR-4698 could target some genes that are overactive in the PI3K/AKT pathway (PI3KCB, PI3KCA, PDK1, AKT1, Rheb, MDM2, mTOR, and CREB1) in glioblastoma." (PMID 32005873, 2020). "PDK1 was the sole gene highly downregulated in both cells tested suggesting that targeting PDK1 and EGFR in mechanisms that bypass TMZ resistance may be a key factor in reverting the Warburg aerobic glycolysis metabolic pattern in glioblastoma." (PMID 28410193, 2017). "In glioblastoma multiforme (GBM), increased levels of the lncRNA that is proximal to X‐inactive (JPX) positively modulate the level of a limiting enzyme of glycolysis, namely PDK1, in an FTO‐dependent manner, thereby contributing to temozolomide chemoresistance." (PMID 38721006, 2024).
prostate carcinoma (31 papers, 2013 to 2026). A carcinoma that arises from epithelial cells of the prostate gland. "In prostate cancer, high expression of hsa-miR-3916 reduced the protein level of pyruvate dehydrogenase kinase 1, thereby reducing the risk of prostate cancer." (PMID 36672150, 2023). "Pathologically, prostate cancer patients associated mutations of SPOP impaired PDK1 degradation and thus activated the AKT kinase, resulting in tumor malignancies." (PMID 34353330, 2021). "Our study analysed the role of the PDK1 gene and functional validation of SNPs and associated miRNAs involved in regulating the PDK1 gene as a mediator of prostate cancer aetiology." (PMID 34298795, 2021). "We sought to identify the role of prostate cancer risk associated SNPs in regulating a vital enzyme of cancer metabolism, pyruvate dehydrogenase kinase 1 (PDK1) via microRNAs." (PMID 34298795, 2021). "OSU was initially associated to an inhibition of PDK1 in prostate cancer cells (PC-3 cells), through a direct binding to its ATP binding site." (PMID 34356673, 2021). "A number of genetic alterations in genes that encode AKT regulators have been linked to prostate cancer, including kinases (e.g., PDK1), binding proteins (e.g., FKBP5), and phosphatases (e.g., PHLPP1, PHLPP2, and PP2A)." (PMID 32630372, 2020). "High E2F1 expression is associated with high levels of GLUT1 and PDK1 in these bladder and prostate cancer datasets." (PMID 25816777, 2015). "We previously discovered the miRSNPs in PDK1 to be associated with the risk of prostate cancer." (PMID 34298795, 2021). "As higher rates of cancer cell migration and invasion are a hallmark of aggressive cancers, our data suggest that PDK1 is a suitable target for therapeutic intervention in prostate cancer and support the clinical development of PDK1 inhibitors for prostate cancer." (PMID 34298795, 2021). "The present study demonstrated that the osteoclast‐specific knockout of PDK1 ameliorated prostate cancer-induced osteolysis and reduced bone resorption markers in the blood in vivo." (PMID 37828580, 2023). "We observed the effect of osteoclast‐specific knockout of PDK1 on prostate cancer-induced osteolysis." (PMID 37828580, 2023). "In general, our research indicated that conditional knockout of PDK1 in osteoclasts in vitro ameliorated prostate cancer-stimulated osteolysis." (PMID 37828580, 2023). "To evaluate the impacts of osteoclast‐specific knockout of PDK1 on prostate cancer-induced osteolysis, we utilized a mouse model of prostate cancer-induced osteolysis." (PMID 37828580, 2023). "To summarize, this research illustrated that the conditional knockout of PDK1 in osteoclasts ameliorated prostate cancer-induced osteolysis effectively by suppressing RANKL-induced bone resorption and osteoclastogenesis." (PMID 37828580, 2023). "Our previous article showed that Cur inhibited the malignant progression of prostate cancer and regulates the PDK1/AKT/mTOR pathway by targeting miR-9." (PMID 35942374, 2022). "Our study found that the suppression of PDK1 reduced the glycolysis, migration, and invasion of prostate cancer cells." (PMID 34298795, 2021). "Herein, we reported that PDK1 suppression decreased prostate cancer cell migration, invasion and glycolysis." (PMID 34298795, 2021). "Although PDK1 mRNA was elevated in prostate cancer cell lines- LNCaP, C42, C42B, LAPC4, 22RV1, DUCaP and DU145 compared with the RWPE1 cellsthe effect was not significant." (PMID 34298795, 2021). "For instance, we reported that inhibition of PDK1 with 2-O-Bn-InsP5 was able to reduce cell numbers in different cancer cell lines as well as growth of prostate cancer PC3 cells in a xenograft model in nude mice." (PMID 31088502, 2019). "Taken together, it was possible that CD44 regulates prostate cancer proliferation, invasion and migration via PDK1 and PFKFB4." (PMID 29029419, 2017).
prostate carcinoma (continued). "The effects of curcumin on breast, as well as pancreatic and prostate cancer cells have been shown to be enhanced when curcumin is combined with 2-O-Bn-InsP5, a specific PDK1 inhibitor." (PMID 29064423, 2017). "Consistent with our findings, addition of a PDK1 inhibitor, dichloroacetate, enhanced metformin response in prostate cancer cells." (PMID 26172303, 2015). "A number of in vitro andin vivo studies in breast and prostate cancer have demonstrated thatMYC amplification or phosphorylation lead to acquired resistance toBEZ235, and Tan andcolleagues used a PDK1 inhibitor to bypass MYC-dependent resistance." (PMID 26678268, 2015). "Western blotting experiments also showed that the protein levels of Akt1, phospho-Akt Ser473, phospho-Akt Thr308, PDK1, c-Myc, Skp2 in prostate cancer cells was decreased by triol treatment." (PMID 23785446, 2013). "Moreover, deletion of PDK1 in osteoclasts ameliorated osteolysis and rPDK1educed bone resorption markers in the murine model of prostate cancer-induced osteolysis." (PMID 37828580, 2023). "Curcumol may also alter the development of prostate cancer via regulating the PDK1/AKT/mTOR signaling pathway via miR-9." (PMID 35889217, 2022). "PDK1 mRNA expression was upregulated in PCa compared to the adjacent prostate gland in two independent datasets: Arredounai (adjacent prostate gland (n = 8), prostate cancer (n = 13)) and Lapointe (adjacent prostate gland (n = 39), prostate cancer (n = 57))." (PMID 34298795, 2021). "Thus, our studies suggest that SPOP would like to play dual functions to modulate AKT kinase activity either by targeting PTEN to activate AKT in ccRCCs or by targeting PDK1 to repress AKT in prostate cancer." (PMID 34353330, 2021). "Our findings provide evidence that PDK1 may contribute to aggressive disease and prostate cancer progression; therefore, PDK1 could be a promising therapeutic target in prostate cancer." (PMID 34298795, 2021). "This presents a potential mechanism for the physiological regulation of PDK1 turnover by E3 ligase SPOP, and further dictate the pathological conditions of prostate cancer, where patients conceived SPOP mutations, or PDK1 degron-associated mutations facilitate tumorigenesis by activating AKT kinase." (PMID 34353330, 2021). "Taken together, CD44 could modulate aggressive phenotype of prostate cancer cells, by regulation of the expression of PDK1 and PFKFB4." (PMID 29029419, 2017). "We found the prostate cancer cells which transfected with PDK1 or PFKFB4 shRNA obtained slower closure of the scratched wound, and the relative cell migration of LNCaP and PC3 cells were decreased significantly compared with the cells infected negative vector control cells and blank cells." (PMID 29029419, 2017). "Therefore, the combination of PDK1 inhibitor with anti-proliferative cancer drugs could be an effective option for treating prostate cancer." (PMID 34298795, 2021). "Western blot analysis indicated DT-13 significantly decreased the phosphorylation of PDK1, Akt, mTOR as well as p70S6K, suggesting the pro-apoptotic and anti-metastatic effects of DT-13 on prostate cancer cells might be attributed to the blockade of PI3K/Akt pathway." (PMID 30581390, 2018). "The histone lysine demethylase KDM4A serves as a coactivator for E2F1, binding to the promoters of PDK1 and PDK3, thus influencing the metabolic transition between glycolysis and mitochondrial oxidation in prostate cancer." (PMID 41158756, 2026). "By contrast, in prostate cancer cells, MALAT1 silencing downregulates ME3, PDK1, PDK3, and choline kinase—enzymes critical for OXPHOS." (PMID 41199749, 2025). "Previously reported oncogenic genes for prostate cancer, including SLC7A11 and pyruvate dehydrogenase kinase 1 (PDK1), were also suppressed after FUBP1 knockdown at both mRNA and protein levels in prostate cancer cells." (PMID 39146021, 2024).